YAP1 (Yes1 associated transcriptional regulator)
Diseases named in the same sentence as YAP1 in open-access papers (continued):
Sharing a sentence is not in itself a finding about the gene and the disease.
tumor (continued). "Others surmised that YAP1 is often the terminal node of many oncogenic pathways and a signaling hub of the tumor microenviroment." (PMID 33588867, 2021). "Multiple mechanisms, such as the TEAD1 signalling pathway, an overexpression of Hedgehog (Hh), suppression by miR-1285-3p, and circFAT1 are involved in the regulation of YAP1 in tumours." (PMID 33803512, 2021). "GPC3 is expressed in all tumor clusters and YAP1 is expressed in all clusters with a slight increase in Tr0." (PMID 34497364, 2021). "Many of the growth-promoting phenotypes observed after YAP1 activation eventually lead to tumor formation, and thus TEADs likely play an integral role in this process." (PMID 34685695, 2021). "Small-cell-lung cancer (SCLC) is associated with overexpression of oncogenes including Myc family genes and YAP1 and inactivation of tumor suppressor genes." (PMID 34439128, 2021). "Yes-associated protein-1 (YAP1) is a transcriptional coactivator and is a pivotal factor in the Hippo/YAP signaling pathway, promoting tumor formation and development." (PMID 34150844, 2021). "Until very recently, it has been difficult to systematically probe the tumor growth requirements for the YAP1/TAZ–TEAD interaction on a broad scale." (PMID 34685695, 2021). "YAP1 was differentially expressed between tumor tissues and normal tissues in multiple cancer types." (PMID 34150844, 2021). "According to a recent study, MYC can act as a master regulator for NE-differentiation and can dynamically shift tumor phenotype acting on the NOTCH signaling pathway from ASCL1 + NEUROD1+ (NE-high) to YAP1+ or POU2F3+ (NE-low)." (PMID 34200100, 2021). "The importance of this crosstalk is further substantiated by the fact that overexpression of YAP1 or β-Catenin alone cannot lead to tumor development in mice, whereas co-expression of the two resulted in rapid carcinogenesis." (PMID 34395416, 2021). "YAP1, a key protein downstream of the Hippo signalling pathway, has been confirmed to play an important role in the malignant progression of tumours." (PMID 34353343, 2021). "Using a tumour tissue microarray, we validated the status of the key factors in the Hippo and mTORC1 pathways using phosphorylated YAP1 and p70S6K." (PMID 34462427, 2021). "Correlations between YAP1 and immune cell infiltration and immune cell marker expression were examined using Tumor Immune Estimation Resource and GEPIA." (PMID 34150844, 2021). "Silencing YAP1 being expressed by CAFs and tumor stromal cells effectively inhibited tumor growth in their study, implying its potency as a therapeutic target." (PMID 33808627, 2021). "In particular, YAP1 stimulates cancer stem cell proliferation and epithelial-mesenchymal transition, induces drug resistance, inhibits apoptosis, and promotes tumor overgrowth." (PMID 33718163, 2021). "Next, to ascertain YAP1 was involved in PWAR6‐mediated tumour‐suppression role in PDAC, we performed a series of rescue experiments in AsPC‐1 and BxPC‐3 cells." (PMID 33834618, 2021). "The results showed that only Ribo-seq UMMD and US showed the up-regulated YAP1 expression, with the expression of YAP1 in Ribo-seq inversely proportional to tumor growth, noticeably, the effect of UMMD treatment on YAP1 expression was the most obvious." (PMID 33996543, 2021).
tumor (continued). "Identification of a tumor with the ST-EPN-YAP1 group is based on detection of either YAP1 rearrangement by FISH or one of the YAP1-fusions (YAP1–MAMLD1, YAP1–FAM118B) by RT-PCR, while IHC with anti-YAP1 and/or anti-Claudin-1 is noninformative." (PMID 34638438, 2021). "Since the genetic or pharmacologic inhibition of YAP1 suppresses tumor progression and improves drug sensitivity, targeting YAP1 is considered as a novel therapeutic target in various cancers." (PMID 35059315, 2021). "The genomic origin of this tumor involves the fusion of chromosome 11 YAP1 gene with chromosome X MAMLD1 gene, though fusion with another gene, FAM 118B." (PMID 34944845, 2021). "It has also been shown that active TGF-β1 affects the activation of Hippo signaling pathway and the function of YAP1, thereby regulating the proliferation of tumor cells." (PMID 35252214, 2021). "The immunofluorescent staining of our local clinical tumor tissue section analyses also showed that the expression of YAP1, LOX, CD68 (human macrophage marker), SPP1, and PD-L1 was enhanced in HSPA7-high GBM tissues compared to HSPA7-low tissues." (PMID 34354698, 2021). "The cancer cell survival suppressive effect of dipyridamole was paralleled by a reduction of the HMGB1/RAGE axis, and proliferation- and migration-related β-catenin, YAP1, Runx2, TGFβ1/Smad, and cyclin D1 in in vitro and in vivo tumor growth models." (PMID 33669632, 2021). "The Hippo signaling is also a tumor suppressor pathway, while YAP1 has been identified as an oncogene in various malignancies associated with tumor progression and poor prognosis." (PMID 34094936, 2021). "Another enriched pathway in both miRNA groups is the Hippo pathway; in MM, the YAP1 protein, which is part of the Hippo pathway, acts as a tumor suppressor, as the rescue of YAP1 has been shown to promote ABL1-dependent apoptosis in hematological malignancies." (PMID 34884950, 2021). "YAP1 silencing suppressed tumor growth in resistant cells, patient-derived xenografts, and EML4–ALK transgenic mice, whereas YAP1 overexpression decreased the responsiveness of parental cells to the ALK inhibitor." (PMID 34685695, 2021). "The hippo-YAP1 axis is a tumor suppressor pathway that can control organ size under homeostatic conditions by regulating cell proliferation and apoptosis." (PMID 34082774, 2021). "MAGIs associate with cell surface receptors, junctional complexes, and interact selectively with a wide range of effectors, including the PTEN tumor suppressor, the β-catenin, and YAP1 proto-oncogenes." (PMID 34503076, 2021). "A previous study showed YAP1 was responsible for the metabolic switch from aerobic glycolysis to OXPHOS to drive up ROS levels in tumor cells." (PMID 34257617, 2021). "Next, we analyzed the correlations between YAP1 and tumor-infiltrating immune cells in the microenvironments of several tumors using TIMER." (PMID 34150844, 2021). "This unique YAP1 high molecular subtype possibly maintains NYC‐GYN's chemorefractory nature that further facilitates immunosuppressive tumor microenvironment." (PMID 34245124, 2021). "Xenograft assays showed that GABABR1 knockdown dramatically increased tumor growth compared with the control group, while YAP1-TEAD inhibition with Peptide 17 reversed tumor volume and weight regardless of the GABABR1 knockdown." (PMID 34131398, 2021). "Array CGH of relapsed tumors identified YAP1 amplification, and enforced expression of YAP1 enabled tumor maintenance following doxycycline withdrawal." (PMID 34680229, 2021).
tumor (continued). "There is accumulating evidence that YAP1 facilitates the immunosuppressive tumor microenvironment, affecting myeloid-derived suppressor cells, macrophages, and regulatory T-cells." (PMID 34150844, 2021). "Studies have shown that YAP1 can recruit M2 macrophages, bone-marrow-derived suppressor cells, and regulatory T cells, thereby inhibiting host-effector T cells in the tumor microenvironment and further leading to cancer progression and drug resistance." (PMID 34394353, 2021). "With this reasoning we tested HOPX in IHC and showed high level of expression in tumours with YAP1-MAMLD1 fusion." (PMID 32404936, 2020). "Yes-associated protein 1 (YAP1) is implicated in Hippo signaling pathway, which is associated with tissue homeostasis and tumor formation." (PMID 33111745, 2020). "Increasing evidence suggests that YAP1 has various roles in tumor growth, immunosuppression, and chemoresistance." (PMID 31963556, 2020). "In the Hippo signaling pathway, there are about 19 central genes with oncogenic and tumor suppressor activities that can interact with studied miRNAs; in this way, the miR-200 family was highlighted as a YAP1 master regulator." (PMID 32766179, 2020). "Knockdown of DLG1-AS1 inhibited cell proliferation, invasion, and migration in vitro, and retarded tumor growth in vivo by regulating the miR-497/YAP1 axis." (PMID 33197895, 2020). "In contrast, +DDR2 tumours displayed higher levels of total YAP1 when compared to -DDR2 tumours (p = 0.057)." (PMID 32047176, 2020). "This non-proteolytic ubiquitination can be reversed by the binding and interaction between deubiquitinase OTUD1 and YAP1; OTUD1 decreases YAP1 stability, and attenuates the cell proliferation and tumor-growth activity of YAP1." (PMID 32390875, 2020). "The YAP1 protein in the tumour stroma can be used as a potential target for tumour diagnosis and treatment." (PMID 32066485, 2020). "Dissemination of circulating tumor cells is crucial for distant metastasis, and YAP1 increases the number of circulating tumor cells following activation by the chromatin remodeling protein ZNF367." (PMID 33178014, 2020). "YAP1 can convert NFs into CAFs in the tumour microenvironment of PCa, thus promoting the development and metastasis of PCa." (PMID 32066485, 2020). "A transplanted tumour model was used to explore the function of YAP1 in regulating tumour growth through stromal cells." (PMID 32066485, 2020). "Yes-associated protein 1 (YAP1), the downstream of the Hippo pathway, has been identified to promote tumorigenesis in different kinds of tumor types." (PMID 32313226, 2020). "One possible explanation is that, in cells possessing few cell-cell contacts, YAP1-2 stabilization in tumor cell contributes to maintain their stemness features." (PMID 32292505, 2020). "Further mechanism investigation revealed that LINC01048 increased the binding of TAF15 to YAP1 promoter to transcriptionally activate YAP1 in tumor cells." (PMID 32674318, 2020). "The high number of tumours in this study allowed to find a clear-cut link between higher YAP1 staining levels and adverse tumour phenotype as well as unfavourable prognosis." (PMID 32488048, 2020). "Yes-related protein 1 (YAP1) is an essential transcription factor and controls several tumor-developing influences, including cancer stemness, metastasis, invasion, migration, epithelial-mesenchymal transition (EMT), chemoresistance, and proliferation." (PMID 32154166, 2020). "As a member of E3 complex, FBXW7 exerted its tumor suppressor function via targeting oncogenes (such as YAP1) for degradation." (PMID 32140077, 2020). "Altogether, the results explained above demonstrated how miR-214-3p OE suppressed LSCC tumor progression by targeting YAP1." (PMID 32863772, 2020). "YAP1 knockdown in BC cell lines suppressed anoikis and increased migration and invasiveness, suggesting its role as a tumor suppressor, which is in line with the decreased expression of YAP1 in BC patients." (PMID 32731349, 2020).
tumor (continued). "This study further demonstrated regulation of Yap-1 levels by β-Catenin at the transcriptional level, and the in vivo findings strongly showed the synergistic effect that mutant CTNNB1 and Yap-1 dual activation had on HB tumor growth." (PMID 31979130, 2020). "That cytoplasmic and nuclear YAP1 staining is equally linked to phenotype and prognosis fits well to a model where YAP1 activation during tumour progression includes up regulation, cytoplasmic accumulation and subsequent translocation to the nucleus." (PMID 32488048, 2020). "The increased stiffness of matricellular tumor microenvironment also activates YAP1 to further modulate the behavior of cancer cells on the transcriptional level." (PMID 32054505, 2020). "The high expression of YAP1 in the tumour stromal cells suggested a poor tumour stage and prognosis in PCa patients." (PMID 32066485, 2020). "Together, targeting FGFR2 by small molecules inhibited YAP1 expression, suppressed tumor growth, and enhanced apoptosis in GC." (PMID 32934314, 2020). "Bioinformatics, loss- and gain- of- function experiments, luciferase reporter assays, chromatin immunoprecipitation (ChIP), and murine tumor xenograft models were performed to examine the function of YAP1 in PDAC and to identify potential mechanisms of action." (PMID 32894161, 2020). "The overexpression of YAP1 during embryonic development leads to oversized organs and eventual tumor formation." (PMID 32292505, 2020). "Patients with high expression of YAP1 in stromal cells tend to have a malignant tumour grade and stage." (PMID 32066485, 2020). "We have demonstrated that fibroblasts with high expression of YAP1 can promote tumour proliferation in vivo." (PMID 32066485, 2020). "This proteolytic ubiquitination can be reversed by deubiquitinases; the deubiquitinase USP9X was shown to directly deubiquitinate and stabilize YAP1, leading to enhanced YAP1 activity and promotion of tumor growth." (PMID 32390875, 2020). "In this feedback loop, YAP1 plays as a decisive factor and is necessary for CAFs to promote tumour proliferation and invasion." (PMID 32066485, 2020). "Our results reveal a novel mechanism of acquired trastuzumab resistance mediated by two pivotal effectors of the Hippo tumor suppressor pathway: the transcriptional co-activator YAP1 and the transcription factors TEAD1-2." (PMID 32365528, 2020). "Third, rescue experiments showed that YAP1 re-expression abrogated the anti-tumor effect of miR-214 on LSCC to a certain extent." (PMID 32863772, 2020). "YAP1 and TAZ, the key components of this signalling pathway, are associated with tumour development in various human cancers." (PMID 32678516, 2020). "To understand the expression of YAP1 protein in tumour epithelial cells and stromal cells, we consulted pathologists to identify the tissue morphology." (PMID 32066485, 2020). "Hippo signaling is also an established tumor suppressor pathway, whereas YAP1 has been identified as an oncogene in various malignant tumors." (PMID 32292505, 2020). "The relationship between the expression of YAP1 in tumour stromal cells and the clinical characteristics of PCa patients was analysed." (PMID 32066485, 2020). "We will continue to study this positive feedback loop and determine the mechanism of YAP1 in the tumour microenvironment." (PMID 32066485, 2020). "Tumor cell secreting exosome containing abundant lncRNA RP11-323N12.5 acting on TILs to stimulate Treg cell differentiation dependent on YAP1 activation, an important factor in Hippo signaling pathways, ultimately promoting immunosuppression and tumor growth." (PMID 33148302, 2020). "miR-375 can reverse the inhibition of YAP1 expression, so that YAP1 to promote the tumor was cut off to this channel to achieve the purpose of inhibiting tumorigenesis." (PMID 32382558, 2020).
tumor (continued). "This study demonstrated that CD33+MDSCs numbers and YAP1 expression levels were increased in tumor tissues compared with those of tumor-adjacent tissues from the same CRC patients." (PMID 33384962, 2020). "This fits well to a model where YAP1 activation during tumour progression includes up regulation, cytoplasmic accumulation and subsequent translocation to the nucleus." (PMID 32488048, 2020). "In PRAD, no significant alteration in mRNA expression of NEK1 was observed, while YAP1 mRNA level was consistently downregulated with respect to the tumor Gleason score." (PMID 33297404, 2020). "In LATS1/2 deletion induced tumours, YAP1 was highly expressed in the cytoplasm of all cells and was enriched in the nucleus in a subset of cells in tumour, in a mosaic fashion." (PMID 32404936, 2020). "Pyruvate kinase M2 (PKM2) is a relevant glycolytic protein; the interaction of YAP1 with hypoxia-inducible factor 1α (HIF-1α) promotes tumor cell glycolysis by triggering the transcription of the Pkm2 gene." (PMID 32390875, 2020). "Tissue‐specific expression of YAP1 in the liver in genetic mice results in liver overgrowth and tumor formation." (PMID 32175692, 2020). "Several reports have demonstrated the potential for VP in suppressing tumor growth and also serving as a research tool to study Hippo/YAP1 functions." (PMID 32175692, 2020). "YAP1 proved to be an important co-regulator of tissue growth, tissue development, tumorigenesis, and tumor metastasis." (PMID 32296329, 2020). "The results showed that in the High-YAP1 group, YAP1 was expressed in the nucleus of 87.65% of tumour cells, while YAP1 was expressed in the nucleus of 80.36% of stromal cells." (PMID 32066485, 2020). "At the same time, it has become evident in the literature that YAP1 can modify the tumor microenvironment by cytokine upregulation." (PMID 32365528, 2020). "YAP1 staining was mainly observed in the nuclei with little staining in the cytoplasm of tumour cells, whereas AGK was only observed in the cytoplasm of tumour cells." (PMID 32827244, 2020). "The animal experiments demonstrated that YAP1 knockdown inhibited nicotine-enhanced tumor growth, and reduced expression of Ki67 and YAP1 (P < 0.01)." (PMID 32894161, 2020). "Some reports proposed Motins as cancer promoters, while some believed that Motins control tumor growth by mediating YAP1." (PMID 32313226, 2020). "The combination of LEE001 and CA3 exhibited the highest anti-tumor effects in radiation-resistant cells overexpressing YAP1 and CDK6 in both in vitro and in vivo by sensitizing resistant tumors to irradiation." (PMID 33665161, 2020). "YAP1 is one of the most important effectors downstream of the Hippo signalling pathway and its aberrant expression that contributes to tumour progression indicates poor outcomes in various cancers." (PMID 33094920, 2020). "The antibody staining specific for YAP1 was detected in the nucleus or in the nucleus and cytoplasm of tumor cells." (PMID 32054505, 2020). "From these results, we found that transcript expression of SAV1 was downregulated by 1.65-fold (p = 0.003), LATS2 by 1.95-fold (p = 0.010) and YAP1 by 1.4-fold (p = 0.007) in tumor samples compared with CC samples." (PMID 32218280, 2020). "When the hippo pathway abnormal YAP1 is activated, YAP1 is a famous oncoprotein, and the incidence of cancer is closely related to the development of the tumor can promote." (PMID 32382558, 2020). "Possibly, the fact that HT1080 xenografts are, in general, highly proliferative tumours, makes it challenging to detect a clear differential subcellular distribution of rapidly shuttling YAP1 by IHC110." (PMID 32047176, 2020). "Here we found that +DDR1b tumours exhibited significantly lower levels of total YAP1 (~75 kDa) when compared to -DDR1b tumours (p = 0.019)." (PMID 32047176, 2020).